HDAC9 (histone deacetylase 9)
Description:
Responsible for the deacetylation of lysine residues on the N-terminal part of the core histones (H2A, H2B, H3 and H4). Histone deacetylation gives a tag for epigenetic repression and plays an important role in transcriptional regulation, cell cycle progression and developmental events. Represses MEF2-dependent transcription. Isoform 3 lacks active site residues and therefore is catalytically inactive. Represses MEF2-dependent transcription by recruiting HDAC1 and/or HDAC3. Seems to inhibit skeletal myogenesis and to be involved in heart development. Protects neurons from apoptosis, both by inhibiting JUN phosphorylation by MAPK10 and by repressing JUN transcription via HDAC1 recruitment to JUN promoter.
Synonyms: HD9; HD7; HD7b; HDAC7B; HDRP; KIAA0744; MITR; HDAC; HDAC9B; HDAC9FL
Tractability: Small molecule: an approved drug acts on it; a high-quality ligand is known; it belongs to a druggable protein family. PROTAC: UniProt records ubiquitination sites on it; ubiquitination databases record sites on it; its protein half-life has been measured; a small molecule that binds it is known. Other modalities: an approved drug acts on it.
Target class: HDAC class IIa; Histone deacetylase; Epigenetic regulator; Eraser
Gene: Protein-coding gene on chromosome 7 (18,086,949 to 19,002,416, forward strand). Ensembl gene ENSG00000048052.
Subcellular location: Nucleus
Subcellular location (Human Protein Atlas): Nucleoplasm; Mitotic chromosome
Pathways (Reactome):
Disease: Constitutive Signaling by NOTCH1 HD+PEST Domain Mutants; Constitutive Signaling by NOTCH1 PEST Domain Mutants
Developmental Biology: Differentiation of naive CD4+ T cells to T helper 2 cells (Th2 cells)
Gene expression (Transcription): Notch-HLH transcription pathway
Signal Transduction: NOTCH1 Intracellular Domain Regulates Transcription
Gene Ontology:
Molecular function: DNA-binding transcription factor binding; histone deacetylase activity; histone deacetylase activity, hydrolytic mechanism; histone deacetylase binding; histone H4K16 deacetylase activity, hydrolytic mechanism; protein binding; protein kinase C binding; protein lysine deacetylase activity; RNA polymerase II-specific DNA-binding transcription factor binding; histone H3K14 deacetylase activity, hydrolytic mechanism; histone H3K9 deacetylase activity, hydrolytic mechanism; transcription corepressor activity
Biological process: cellular response to insulin stimulus; cholesterol homeostasis; negative regulation of cytokine production; negative regulation of DNA-templated transcription; negative regulation of gene expression, epigenetic; negative regulation of transcription by RNA polymerase II; positive regulation of cell migration involved in sprouting angiogenesis; B cell activation; B cell differentiation; heart development; inflammatory response; regulation of skeletal muscle fiber development; regulation of striated muscle cell differentiation
Cellular component: cytoplasm; nucleus; transcription regulator complex; histone deacetylase complex; histone methyltransferase complex; nucleoplasm
Genetic constraint (gnomAD): Loss-of-function variants: 30 observed, 108.03 expected, observed/expected ratio (o/e) 0.28, 90% interval 0.21 to 0.38. The upper end of that interval is the gene's LOEUF score, 0.38, which puts it in group 1 of 6, group 1 being the genes least tolerant of losing a copy. Missense variants: 964 observed, 1,098.7 expected, observed/expected ratio (o/e) 0.88, 90% interval 0.83 to 0.93. Synonymous variants: 444 observed, 413 expected, observed/expected ratio (o/e) 1.08, 90% interval 0.99 to 1.16.
Gene-disease validity (ClinGen):
ClinGen rates the evidence that HDAC9 causes each of these diseases.
auriculocondylar syndrome (autosomal dominant): Disputed. Auriculo-condylar syndrome (ACS) presents with bilateral external ear malformations ('question mark' ears), mandibular condyle hypoplasia, microstomia, micrognathia, microglossia and facial asymmetry.
Homologues: Orthologues: chimpanzee HDAC9 (99% identical), dog HDAC9 (98% identical), pig HDAC9 (98% identical), rabbit HDAC9 (96% identical), macaque HDAC9 (93% identical), rat Hdac9 (92% identical), mouse Hdac9 (92% identical), guinea pig HDAC9 (91% identical), tropical clawed frog hdac9 (40% identical), Drosophila melanogaster HDAC4 (39% identical), zebrafish hdac9b (31% identical), Caenorhabditis elegans hda-4 (29% identical), and 3 more. Paralogues in human: HDAC5 (60% identical), HDAC4 (58% identical), HDAC7 (41% identical), HDAC6 (22% identical), HDAC1 (11% identical), HDAC10 (11% identical), HDAC2 (11% identical), HDAC3 (10% identical), HDAC11 (10% identical), HDAC8 (9% identical).
Diseases named in the same sentence as HDAC9 in open-access papers:
HDAC9 is named in the same sentence as 650 diseases in open-access papers, as found by Europe PMC text mining. Sharing a sentence is not in itself a finding about the gene and the disease. The quoted sentences say what the papers report.
breast carcinoma (444 papers, 2005 to 2026). "HDAC9 overexpression has been linked to cell growth in medulloblastoma, lymphoma, oral squamous cell carcinoma, and breast cancer." (PMID 35865469, 2022). "Abnormal expression of HDAC9 has been found in a variety of tumors; overexpression of HDAC9 is associated with poor prognosis for patients with breast cancer, glioblastoma, and non-small cell lung cancer." (PMID 35203583, 2022). "In contrast to prior results from breast cancer cell-lines, the median HDAC9 expression is positively associated with ER levels in our TMA clinical samples." (PMID 35226658, 2022). "HDAC9 expression is positively associated with up-regulated genes in endocrine therapy-resistant breast cancer, and high HDAC9 levels are associated with poorer prognosis in patients treated with OHTam." (PMID 36171897, 2022). "In other tumors, high expression of HDAC9 was usually associated with poor prognosis in patients, such as pancreatic cancer, breast cancer, and oral squamous cancer." (PMID 36072664, 2022). "High incidence of class IIa HDACs (HDAC4, HDAC5 and HDAC9), is associated with colorectal and breast cancers." (PMID 30691229, 2019). "Our study underlines strong interactions between class IIa HDAC9 and ERα signaling and undercovers the key role of HDAC9 in antiestrogen resistance of breast cancer cells and tumors." (PMID 31099456, 2019). "In TN breast cancer patients treated with chemotherapy, rs2285440 (A > C), rs1726599 (C > A) and rs6956139 (C > A) in moderate LD (r2 ≥ 0.38) located in HDAC9 showed associations with two-fold increased HRs (HR 1.92 to 2.41, P <10−3)." (PMID 25849327, 2015). "The precise mechanisms involved remain to be determined, although loss of ERα expression could contribute to HDAC9 upregulation in antiestrogen‐resistant breast cancer cell lines." (PMID 31099456, 2019). "Finally, HDAC9 expression was positively associated with genes upregulated in endocrine therapy‐resistant breast cancers and high HDAC9 levels were associated with worse prognosis in patients treated with OHTam." (PMID 31099456, 2019). "As ERα expression is lost or decreased in OHTR cells, we next asked whether breast cancer cell resistance to OHTam could be associated with changes in HDAC9 gene expression." (PMID 31099456, 2019). "Moreover, some studies have noted that overexpression of HDAC9 is associated with poor prognosis and tumor progression of breast cancer and acute lymphoblastic leukemia." (PMID 31365693, 2019). "We also observed the association of HDAC9 with OHTam resistance in breast cancer samples." (PMID 31099456, 2019). "Accordingly, analysis of mRNA levels for the longer HDAC9 mRNA isoforms (variants 1, 4 and 5) and the deleted HDAC9ΔCD isoform (variant 3) showed similar profiles in various breast cancer cells, suggesting that the deregulation of HDAC9 expression mainly occurs at the transcriptional level." (PMID 26930713, 2016). "Finally, to determine whether HDAC9 expression was associated with patient survival, we used the Breast Cancer Gene-Expression Miner v3 statistical mining module." (PMID 26930713, 2016). "Increased expression of HDAC9 has been shown to be associated with decreased expression and activity of estrogen receptor alpha in MCF-7 cells in breast cancer studies." (PMID 40182431, 2025). "For example, antiproliferative effects of melatonin occurred via downregulation of oncogenic factors, such as cyclin D1 in MCF-7 breast cancer cells or of histone deacetylase 9 (HDAC9) in non–small cell lung cancer." (PMID 38730600, 2024). "HDAC9 decreased ER-alpha mRNA and protein expression, and inhibited its transcriptional activity in breast cancer cell lines." (PMID 35226658, 2022). "miRNA-30c triggers chemoresistance in breast cancer cells via histone deacetylase 9 (HDAC9) upregulation." (PMID 33670518, 2021). "In our study, we found that MITR was the main isoform of HDAC9 in cultured mammary cancer cells and TNBC tumors." (PMID 33042272, 2020).
breast carcinoma (continued). "For example, by reducing HDAC9 expression, miR-101-3p, miR-206, and miR-377 prevent the progression and development of retinoblastoma, breast cancer, and OSCC, respectively." (PMID 31365693, 2019). "Altogether, these results demonstrated that HDAC9 inhibits ERα expression and activity in human breast cancer cells." (PMID 31099456, 2019). "Here, we investigated the role of HDAC9 in ERα signaling and response to antiestrogens in breast cancer cells." (PMID 31099456, 2019). "Overexpression of HDAC9 was reported in medulloblastoma, lymphoma, oral squamous cell carcinoma, retinoblastoma, and breast cancer and was shown to promote cell growth." (PMID 31451695, 2019). "In MCF7 breast cancer cells, HDAC9 decreased ERα mRNA and protein expression and inhibited its transcriptional activity." (PMID 31099456, 2019). "In the pathological process of cancer, HDAC9, as an oncogene, confers migratory, invasive, and angiogenic potential in various malignancies, including breast cancer, oral squamous cell carcinoma (OSCC), lymphoma, and medulloblastoma." (PMID 31365693, 2019). "Here, we demonstrated the strong interaction of class IIa HDAC9 with ERα signaling and its implication in OHTam resistance in breast cancer cell lines and tumor samples." (PMID 31099456, 2019). "Our results demonstrate that HDAC9 overexpression in Michigan Cancer Foundation‐7 (MCF7) breast cancer cells modulates ERα expression and activity and alters ERα ligand effect on cell proliferation." (PMID 31099456, 2019). "Altogether, these data clearly supported a link between HDAC9 overexpression and antiestrogen resistance in breast cancer cells." (PMID 31099456, 2019). "Altogether, these results argue for an important role of HDAC9 overexpression in the acquisition of tamoxifen resistance by breast cancer cells." (PMID 31099456, 2019). "Here, we investigated HDAC9 role in ERα signaling in breast cancer cells and its expression in antiestrogen‐resistant breast cancer cell lines." (PMID 31099456, 2019). "Altogether, this work highlights strong interactions between class IIa HDAC9 and ERα signaling, suggesting a key role of HDAC9 in antiestrogen resistance of breast cancers." (PMID 31099456, 2019). "In contrast to that, HDAC9 is overexpressed in the tumor tissues from breast cancer, OSCC, and retinoblastoma, and inhibition of HDAC9 suppresses cancer cell proliferation, migration, and invasion." (PMID 31365693, 2019). "Altogether, these results supported our in vitro data and demonstrated the prognostic value of HDAC9 levels in patients with breast cancer who received antiestrogen therapy." (PMID 31099456, 2019). "We then showed that HDAC9 overexpression decreases the sensitivity of MCF7 breast cancer cells to ER ligands in proliferation assays." (PMID 31099456, 2019). "Altogether these results demonstrate that the SOX9 gene is an HDAC9 target gene, which controls its mitogenic effect in breast cancer cells." (PMID 26930713, 2016). "Altogether, these data demonstrate that HDAC9 is a strong regulator of breast cancer cell proliferation and survival." (PMID 26930713, 2016). "Altogether, these data demonstrated that HDAC9 expression was significantly increased at the mRNA and protein levels in basal breast cancer cells, which exhibit the most aggressive phenotype." (PMID 26930713, 2016). "Our data also indicate that deregulated expression of HDAC9 in breast cancer cells (ectopic expression in MCF7 cells and knock-down in MDA-MB436 cells) alters gene expression, cell proliferation and apoptosis." (PMID 26930713, 2016). "We investigated the mechanisms by which the HDAC9 gene is overexpressed in basal breast cancer cells." (PMID 26930713, 2016). "The effect of HDAC9 on cell proliferation is coupled to a reduced sensitivity of breast cancer cells to the antiproliferative and apoptotic activity of HDIs, similar to that observed in cells of basal type as compared to luminal ones." (PMID 26930713, 2016).
breast carcinoma (continued). "Our data demonstrated that the overexpression of HDAC9 in the most aggressive breast cancer cells influences cell homeostasis with an increase in cell proliferation and a decrease in programmed cell death." (PMID 26930713, 2016). "Altogether, this work evidences an important role of HDAC9 in breast cancer cells and in their response to HDAC inhibitors." (PMID 26930713, 2016). "Most importantly, HDAC9 expression controls the sensitivity of breast cancer cells to HDAC inhibitors." (PMID 26930713, 2016). "To identify HDAC9 target genes in breast cancer cells, we performed a global transcriptome analysis of MCF7-Control and MCF7-HDAC9FL cells." (PMID 26930713, 2016). "Ectopic expression of HDAC9 in MCF7 luminal breast cancer cells led to an increase in cell proliferation and to a decrease in apoptosis." (PMID 26930713, 2016). "To validate our in vitro data and to characterize HDAC9 expression in tumors from patients, we first reanalyzed a cDNA array data set containing 184 breast cancers mRNA profiles (NKI dataset)." (PMID 26930713, 2016). "Altogether these data strengthened our in vitro results concerning the correlation between HDAC9 and SOX9, their higher expression in basal type breast cancers and the deleterious effect of HDAC9 overexpression on breast cancer cell proliferation." (PMID 26930713, 2016). "The impact of HDAC9 on cell proliferation was also assessed by knocking-down its expression in basal breast cancer cells using small interfering RNA." (PMID 26930713, 2016). "We next performed run-on experiments using luminal MCF7 and basal MDA-MB436 cell lines to compare HDAC9 gene transcription rate in both groups of mammary tumor cells." (PMID 26930713, 2016). "In this study, we first demonstrate that class IIa HDAC9 expression is markedly increased at the transcriptional level in the most aggressive mammary tumor cell lines." (PMID 26930713, 2016). "One isoform is the full-length form of HDAC9, with low expression in breast cancer cell lines." (PMID 33042272, 2020). "We recently reported that HDAC9 mRNA expression is markedly increased in the most aggressive breast cancer cell lines, and that HDAC9 expression deregulation (ectopic expression and knockdown) in breast cancer cells significantly alters gene expression, cell proliferation and response to HDIs." (PMID 31099456, 2019). "Other mechanisms could explain HDAC9 gene upregulation in ER‐negative and in antiestrogen‐resistant breast cancer cells." (PMID 31099456, 2019). "Altogether, these data suggested that HDAC9 represses estrogen signaling in breast cancer cells." (PMID 31099456, 2019). "HDAC9 plays also an important role in various type of cancers including, among others, oral squamous cell carcinoma, retinoblastoma and breast cancer." (PMID 31099456, 2019). "Moreover, HDAC9 expression was markedly deregulated in antiestrogen‐resistant mammary tumor cell lines." (PMID 31099456, 2019). "Finally, we identified SOX9 as an HDAC9 target gene in breast cancer cells which supports, at least partly, its mitogenic activity." (PMID 26930713, 2016). "Our results demonstrate that class IIa HDAC9 may have a specific role in breast carcinoma as it is overexpressed in the most aggressive breast tumor cell lines and tumors, stimulates cell proliferation and increases resistance to HDAC inhibitors." (PMID 26930713, 2016). "HDAC9 mRNA levels were strongly expressed in MCF7-HDAC9FL cells although the levels appeared still very low as compared to those found in MDA-436 basal human breast cancer cells." (PMID 26930713, 2016). "Finally, we identified the SOX9 gene as a new HDAC9 target gene which explained, at least partly, the effect of HDAC9 on breast cancer cell proliferation." (PMID 26930713, 2016). "Finally, in a large panel of breast cancer biopsies, HDAC9 expression was significantly increased in tumors of the basal subtype, correlated with SOX9 expression and associated with poor prognosis." (PMID 26930713, 2016).
breast carcinoma (continued). "In this study, we observed a strong overexpression of class IIa HDAC9, at the mRNA and protein levels, in the most aggressive human breast cancer cell lines (i.e. in basal breast cancer cells vs luminal ones or in malignant vs begnin MCF10A breast epithelial cell lines)." (PMID 26930713, 2016). "Here, to determine whether HDAC9 also modulates ERα signaling in breast cancer cells, a luciferase reporter assays was used to test the activity of a 4‐kb fragment of the ERα promoter in MCF7 breast cancer cells transfected or not with a plasmid that expresses HDAC9FL." (PMID 31099456, 2019). "Indeed, HDAC9 expression is increased upon ERα silencing in breast cancer cell lines." (PMID 31099456, 2019). "We also note that TMP195, a first-in-class highly selective class II HDAC inhibitor, has shown potent activity in breast cancer mouse model studies, making it an attractive candidate to test in JMML patients who display increased HDAC5 and HDAC9 activity." (PMID 37958378, 2023). "In breast cancer progression, miRNA-30 c also play a role by inhibiting KRAS signaling, histone deacetylase 9 (HDAC9), or coactosin-like protein 1 (COTL1)." (PMID 34503377, 2021). "We further analyzed HDAC9 mRNA transcripts in the TNBC samples from FUSCC TNBC dataset 38 and found MITR expression to be much higher than full-length HDAC9a isoform in tumors, consistent with mammary cancer cell line results." (PMID 33042272, 2020). "Low or no HDAC9 signal was detected in the luminal breast cancer cells analyzed, whereas the anti-HDAC9 antibody detected high levels of a protein around 95 kDa in the basal cell lines tested." (PMID 26930713, 2016). "Moreover, our analysis of publicly available cDNA array data showed a significant increase in HDAC9 mRNA levels in ERα‐negative tumors compared with ERα‐positive samples, validating the biological relevance of the results obtained in breast cancer cell lines." (PMID 31099456, 2019). "We previously reported that HDAC9 expression was significantly lower in ERα‐positive breast cancer cell lines, such as MCF7 and T47D, compared with ERα‐negative breast cancer cell lines, such as MDA‐MB231 and MDA‐MB436." (PMID 31099456, 2019). "In order to define whether SOX9 mediated the mitogenic effect of HDAC9 in breast cancer cells, we modulated SOX9 gene expression in MCF7 cells overexpressing or not HDAC9." (PMID 26930713, 2016).
melanoma (188 papers, 2006 to 2026). A malignant, usually aggressive tumor composed of atypical, neoplastic melanocytes. "Thus, AKT3, HDAC9, TCF12, and LEF1 were differentially expressed in the melanoma specimens, tracking with CD271 enrichment." (PMID 31118427, 2019).
prostate carcinoma (171 papers, 2006 to 2026). A carcinoma that arises from epithelial cells of the prostate gland. "Copy number variations in regions encompassing important prostate cancer genes, such as PTEN and CHD1 or ASAP1, MYC, and HDAC9, are predictive of cancer significance and represent useful biomarkers to distinguish low-risk prostate cancer from intermediate- and high-risk prostate cancer." (PMID 31366128, 2019).